NF1 (neurofibromin 1)
Diseases named in the same sentence as NF1 in open-access papers (continued):
Sharing a sentence is not in itself a finding about the gene and the disease.
tumor (continued). "There is no consensus on the optimal management of childhood LGG: the decision to treat a patient with OPG depends on age, NF1 status, tumor size, tumor localization and, most significantly, on the impact of the tumor on neurological and visual functions and consequent functional deficits." (PMID 36831379, 2023). "Moreover, these tumors arose in immunocompetent mice allowing the interrogation into the tumor-immune axis that was necessary in NF1-OPG formation." (PMID 38318325, 2023). "In addition, combined PLCγ and MEK inhibition blocked the AZD6244-induced reduction in NF1 expression and reactivation of ERK and simultaneously restored the susceptibility of tumor cells to AZD6244 treatment." (PMID 37355626, 2023). "In PBS-treated Nf1-deleted tumors, we observed sex-dependent tumor growth patterns." (PMID 36826025, 2023). "scRNA-Seq of PDGFB and Nf1 mGBM revealed that Nf1 mGBM cells are more prominent contributors to the total pool of MCP transcripts compared with PDGFB tumor cells, further supporting the observation that Nf1-silenced mGBM cells express high levels of MCPs to recruit monocytes." (PMID 37733448, 2023). "Nf1 KO itself promoted tumor formation, which is consistent with its tumor suppressor role." (PMID 36241718, 2023). "Finally, we discuss the psychosocial support for people with NF1 during tumour surveillance and management." (PMID 36684394, 2023). "In xenograft models, the tumour volume of the NF1 suppress group increased faster than the control group in the shRNA‐NC group or shIGF2BP3 group, and the same result was shown in the control group tumour weights." (PMID 37743642, 2023). "In conclusion, we have demonstrated that a new mouse model of ERMS driven by the loss of Nf1 and Ink4a/Arf histologically resembles previously-published ERMS models while also displaying unique features, including delayed tumor initiation and sex-dependent growth patterns." (PMID 36826025, 2023). "However, this association has now been confuted, as recently reported by the ERN GENTURIS tumor surveillance guidelines for individuals with NF1." (PMID 36831560, 2023). "We also incorporated the tumour-related psychosocial and quality of life impact of NF1." (PMID 36684394, 2023). "Nevertheless, we asked whether genetically ablating Cxcl1 in qMCP−/−;Ntv-a mice can extend the survival of Nf1-tumor-bearing mice." (PMID 37012245, 2023). "An experimental model of low-grade optic gliomas with mutation of neurofibromin 1 (NF1) showed increased expression of chemokine C-C ligand 5 (CCL5), along with other chemokines responsible for tumor growth, and increased attraction of T cells and microglia into tumor tissue." (PMID 38275375, 2023). "Neurofibromatosis type 1 (NF1) is an autosomal dominant condition, with a birth incidence of approximately 1:2000–3000, caused by germline pathogenic variants in NF1, a tumor suppressor gene encoding neurofibromin, a negative regulator of the RAS/MAPK pathway." (PMID 36831560, 2023). "Nonetheless, they necessitate neuro-radiological and ophthalmological surveillance, with intervals that vary (quarterly, semi-annually, or annually) contingent upon the tumor’s location, documented symptoms, and the presence or absence of NF-1 association." (PMID 37830595, 2023). "NF1 protein levels in baseline tumors (tumor content 50%–80%) were determined by KIPA-SureQuant." (PMID 37501682, 2023).
tumor (continued). "This was further corroborated in our cohort with patients undergoing GTR of tumor, low grade tumor pathology on histology, and absence of NF-1 mutation trending toward having an improved OS." (PMID 37880773, 2023). "Additionally, when combined treatments were performed based on verteporfin and selumetinib, synergistic effects were observed on cytotoxicity of NF1 related pNF tumor cells in vitro and in vivo xenograft models." (PMID 36619222, 2023). "Where appropriate, we adapted recommendations to different age groups, individuals with different types of pathogenic variants in NF1 or to pre-existing medical history that might influence risks for a specific tumour type in NF1." (PMID 36684394, 2023). "In addition, H3-K27 FGFR1MUT tumours presented often other hits in the MAPK pathway with NF1 (13/31; 42%) or PTPN11 in (3/22; 13.6%) as the topmost mutated genes." (PMID 38066305, 2023). "NEO cells were confirmed by inference of aneuploidy (InferCNV), showing chromosomal loss profiles concordant with SNP-array data (where available) and loss of heterozygosity for PCPG tumor-suppressor driver genes including VHL (chr3p), NF1 (chr17q), TMEM127 (chr2q) and SDHB (chr1p)." (PMID 36271074, 2022). "The NF1 protein is a tumor suppressor that inhibits the activity of the NRAS oncogene." (PMID 35565444, 2022). "First, a different tumor distribution pattern was found in NF1 + OPG and spOPG patients." (PMID 34994964, 2022). "As observed, the clinical phenotypes associated with NF1 are numerous and include both tumor and nontumor symptoms." (PMID 35506373, 2022). "NF1 p.L43L mutation in TCGA-39-5040 had an over-expressing mutant allele (DNA VAF: 0.32, RNA VAF: 0.63) and showed an upregulated gene expression (tumor/paired-normal fold change: 2.53), which activated NF1 function to under-regulate the RAS signaling pathway and suppressed carcinogenesis." (PMID 35846154, 2022). "Therefore, the tumor suppressive function of NF1 is considered to be mainly dependent on its downregulation of the proto-oncogene RAS." (PMID 36211008, 2022). "Biopsies or partial tumor resection was performed in 9 patients (3 NF1 + OPGs)." (PMID 34994964, 2022). "As a tumor suppressor gene, NF-1 may restrict the rapid and abnormal growth and differentiation of neural cells." (PMID 36241865, 2022). "Expression of several tumor suppressors was reduced with NF1 being lost frequently." (PMID 34967922, 2022). "Malignant peripheral nerve sheath tumor is the most common tumor in patients with NF1." (PMID 35490251, 2022). "This tumor showed LOH on the long arm of chromosome 17 including the NF1 locus." (PMID 36760809, 2022). "The analysis confirmed a higher mutational burden in the Non-Resp group with more deleterious alterations in the PTEN, RB1, and NF1 genes, which are well-known tumor suppressor genes in GB, indicating a more aggressive phenotype in accordance with our previous results." (PMID 36132155, 2022). "NF1 is a tumor suppressor that regulates RAS via modulating GTPase activity." (PMID 35130920, 2022). "NF1 and NF2 encode tumour suppressors that have been experimentally implicated in RAF inhibitor resistance in epithelial cancer cells and downregulation of either or both Nf1 or Nf2 in Ba/F3 cells stably expressing BRAFV600E conferred vemurafenib resistance in vitro." (PMID 35158965, 2022).
tumor (continued). "Here, we applied genomic DNA sequencing to NF1-derived tumors and identified additional genetic alterations in PTPN11 (encoding Src homology region 2 domain-containing phosphatase-2 (SHP)-2) and BRAP associated with NF1 tumor malignancy." (PMID 35625983, 2022). "In the same vein, pathogenic missense variants affecting NF1 residue Met1149 are associated with a mild phenotype characterized by the lack of NF1-associated tumours." (PMID 34928431, 2022). "Key findings of the present work are the identification of a complex bioenergetic adaptation in mitochondria of neurofibromin-deficient cells and the demonstration that a multiple rewiring in respiratory function contributes to the tumorigenic potential of NF1-related neoplasms." (PMID 35393510, 2022). "The NF1 gene is a tumor suppressor gene that is located on the long armof chromosome 17." (PMID 35210668, 2022). "Ningning Chen at Sun Yat-sen University in Shenzhen, China, and co-workers hypthesized that a tumor suppressor gene called NF-1 may restrict the rapid growth and differentiation of transplanted neural stem cells." (PMID 36241865, 2022). "This may explain the observation that while multiple drugs inhibit the hyperactive RAS/MEK signaling of NF1 tumor cells in cell culture, most tyrosine kinase inhibitors fail in vivo and in clinical trials." (PMID 35741605, 2022). "The novel NF1 variant (c.6361T > G (p.Ser2121Ala) and NSD1 variant (c.5924T > A; p.Leu1975His), occurring within the highly conserved SET domain, were instead exclusively identified in the recurrent tumor." (PMID 36611369, 2022). "The inclusion or exclusion of NF-1 patients, variation in patient age and tumor status (newly diagnosed or recurrent), in addition to versatility in tumor site and response to treatment’s definitions, and progression interpretation all restrict comparisons across various CT regimens." (PMID 36230704, 2022). "Of these, only COL1A2 was elevated in the CM from the tumor-associated group 1, but not in the non-tumor-associated group 2, hiPSC-sensory neurons, as well as in mouse Nf1+/neo but not Nf1+/1809 DRG neurons (2.4–3.2-fold increase)." (PMID 35589737, 2022). "Tumor load measurements on T2-weighted images, in particular of the optic nerve width, may be sufficient in both NF1 + OPGs and spOPGs." (PMID 34994964, 2022). "When we profiled one of the tumours carrying mutations in NF1 and DLST, it clustered together with DLST-mutated tumours and separated from cluster 2 samples (including one NF1-mutated PCC), suggesting a role of the DLST variant in the observed molecular phenotype." (PMID 36760809, 2022). "NF1 alterations are approximately doubled in metastatic lesions compared with the primary tumor." (PMID 36358725, 2022). "Moreover, a recent study described the co-existence of NF1 germline mutations and ATRX somatic alterations in different tumours from NF1 patients." (PMID 36760809, 2022). "For example, NF1 is a tumor suppressor that negatively regulates RAS signaling." (PMID 35846154, 2022). "Biallelic activation for Nf1 in astrocytes depends on haploinsufficient stromal cells to develop a tumor, while biallelic activation in earlier progenitor cells bypasses such dependency suggesting that timing of the mutation determines the NF1 required dosage to develop tumors." (PMID 34359780, 2021). "The tumor suppressor NF1 is active for the purpose of controlling tumor growth." (PMID 33902757, 2021). "Loss of NF1 increases glycolysis and decreases respiration via mitochondrial ERK signaling, which may play a role in tumor growth." (PMID 34257279, 2021).
tumor (continued). "Ophthalmological examinations including age specific monitoring of NF1-OPG manifestations are important, as risk factors for visual impairment are a diagnosis of OPG below the age of two years, tumor involvement of the posterior optic tract and germline NF1 pathogenic variations." (PMID 34809690, 2021). "Hemizygosity for this microRNA gene may therefore facilitate tumour growth in those patients with NF1 microdeletions that encompass it." (PMID 34535841, 2021). "Taken together, these results demonstrate that T cells from Nf1OPG mice treated with HDM or OVA produce decorin, which impairs the ability of T cells to stimulate microglia, thus interfering with a tumor supportive microenvironment for murine Nf1-optic glioma formation." (PMID 34880260, 2021). "In our study, in order to find the internal reference genes stably expressed in different NF1 samples, we investigated fourteen different NF1 related cell lines, which include two non-tumor NF1+/- Schwann cell lines, five pNF cell lines and seven MPNST cell lines." (PMID 33630851, 2021). "Moreover, the xenograft model derived from NF1-MPNST overexpressing miR-612 showed decreased tumor volume and proliferative markers." (PMID 34359780, 2021). "Trametinib treatment resulted in tumor growth reduction in murine models of NF1-null MPNST34." (PMID 33580196, 2021). "Concomitant loss of NF1 and TAOK1 resulted in tumor formation in vivo." (PMID 33808166, 2021). "Recently, CRISPR/Cas9 has also been utilized in NF1-related tumor models." (PMID 34359780, 2021). "Therefore, in contrast with CRL1 complex regulating the degradation of many tumor suppressors, such as p21, p27, Iκ-Bα and NF1, CRL2 seems to mainly target oncogenic substrates for degradation." (PMID 33504946, 2021). "Consequently, the NF1 minipig provides the ideal platform for developing new imaging strategies for the detection and longitudinal evaluation of NF1 tumor dynamics." (PMID 33669386, 2021). "MEKi therapy remodels the kinome activity and gene expression in NF1 mutant tumor cells." (PMID 33863389, 2021). "NF1 is a tumor suppressor gene that negatively regulates RAS signaling." (PMID 34195081, 2021). "Unlike humans, these models do not develop the hallmark features of NF1 such as PN and nervous system tumors which makes them not useful for NF1 related tumor studies." (PMID 34359780, 2021). "Therefore, inhibitors of pro-survival BCL2 family proteins should have a therapeutic index based on synergy with the effects of sirolimus in targeted therapy for “primed” NF1/PTEN-mutant tumor cells, while sparing normal tissues." (PMID 34331013, 2021). "Furthermore, the whole-body tumor volume in our control group (49 ml) was similar to the tumor volume of the general NF1 population previously reported (18.7–107.9 ml)." (PMID 33951044, 2021). "Molecular examination of the tumor showed a truncating NF1 mutation, absence of BRAFV600 hotspot mutation and CDKN2A/B deletion." (PMID 33905054, 2021). "However, in that study the prevalence of patients with a high tumor burden (> 3000 ml) was significantly increased in patients with NF1 whole gene deletions." (PMID 33951044, 2021). "Besides tumor-related manifestations, NF1 is also characterized by a wide spectrum of CNS alterations, with variable impacts on functioning and life quality, which can be observed to varying degrees in up to 70% patients." (PMID 33921292, 2021).
tumor (continued). "Neurofibromatosis type 1 (NF1) is a tumour suppressor gene located at 17q11.2." (PMID 34680938, 2021). "Previous studies have shown that NF1 whole gene deletions can be associated with a higher tumor burden in affected patients compared with patients without large deletions." (PMID 33951044, 2021). "Patients with higher tumor burden will in turn have a relatively higher risk to develop MPNSTs and other severe features than non-deletion NF1 patients." (PMID 34566848, 2021). "Mechanistically, Nf1 heterozygosity appears to render mast cells more sensitive to Kit ligand, which attracts them to peripheral nerves and likely regulates their expansion and/or survival within the growing tumor." (PMID 33708774, 2021). "Two gCIS, Nf1 and Trps1, show synthetic haploinsufficient tumor suppressor activity." (PMID 34475389, 2021). "Interestingly, only approximately 15%–20% of patients with NF1 develop optic glioma, sometimes as the first sign of subtle NF1 (Kebudiet al., 2008) and 10% of these children will have tumor progression." (PMID 32533764, 2020). "The NF1 gene is a negative regulator of RAS oncoprotein with tumor suppressor function." (PMID 32887687, 2020). "This could be explained by the early stage of detection of Cluster 2 due to other manifestations of the germline especially NF1 and then the smallest size of cluster 2 compared with sporadic tumours." (PMID 32859070, 2020). "It is also possible that heterozygosity may, in some cases, play an antagonistic role in tumor initiation and malignant transformation (even while accelerating the formation of benign neoplasms), as shown for NF1." (PMID 32066498, 2020). "In addition, we will perform multiregional analysis and temporal sampling, with the same methodologies, on a subset of nine subjects with NF1-related MPNSTs to assess tumor heterogeneity and cancer evolution." (PMID 32252413, 2020). "The NF1 gene was initially discovered as a tumor suppressor in the early 1990s." (PMID 33061844, 2020). "Future work is aimed at deciphering the contribution of the Hippo pathway, the JAK/STAT pathway and oestrogen signalling, as well as interfering with cells in the microenvironment that modulate tumour progression, such as nerve cells, T cells, macrophages and Nf1+/– stromal cells." (PMID 32439933, 2020). "It has previously been described in the murine system that Suz12 acts as a tumor suppressor in Nf1-deficient but not in Nf1-wild-type tumors." (PMID 32651197, 2020). "Moreover, 16 of the top 20 CIS genes had supporting fusion transcripts from at least one tumor, including Cdkn2a, Nf1, Pten, Sox6, Sox5, Spred1, and Tcf12 (all containing PB splice acceptor fusions, implying transcript termination)." (PMID 32727536, 2020). "A direct comparison between sporadic MPNST and NF1-derived MPNST revealed that these two tumor types could be completely distinguished on the basis of their miRNA expression profiles." (PMID 32076030, 2020).